MAP1B (microtubule associated protein 1B)
Description:
Facilitates tyrosination of alpha-tubulin in neuronal microtubules (By similarity). Phosphorylated MAP1B is required for proper microtubule dynamics and plays a role in the cytoskeletal changes that accompany neuronal differentiation and neurite extension. Possibly MAP1B binds to at least two tubulin subunits in the polymer, and this bridging of subunits might be involved in nucleating microtubule polymerization and in stabilizing microtubules. Acts as a positive cofactor in DAPK1-mediated autophagic vesicle formation and membrane blebbing.
Synonyms: MAP5; PPP1R102; DFNA83; FUTSCH; PVNH9
Tractability: Antibody: its Gene Ontology location is reachable by antibodies, with high confidence. PROTAC: ubiquitination databases record sites on it; its protein half-life has been measured; a small molecule that binds it is known.
Target class: Other cytosolic protein
Gene: Protein-coding gene on chromosome 5 (72,107,234 to 72,209,565, forward strand). Ensembl gene ENSG00000131711.
Subcellular location: Cytoplasm, cytoskeleton; Cytoplasm; Synapse; Cell projection, dendritic spine; Cytoplasm (MAP1 light chain LC1)
Subcellular location (Human Protein Atlas): Cytosol; Equatorial segment
Pathways (Reactome):
Disease: RSV-host interactions
Gene Ontology:
Molecular function: protein binding; actin binding; microtubule binding; structural molecule activity; phospholipid binding; protein-containing complex binding
Biological process: neuron projection development; odontoblast differentiation; axon extension; axonogenesis; dendrite development; microtubule cytoskeleton organization; neuron migration; regulation of microtubule depolymerization; cellular response to growth factor stimulus; cellular response to peptide hormone stimulus; developmental maturation; induction of synaptic plasticity by chemical substance; microtubule bundle formation; negative regulation of microtubule depolymerization; nervous system development; neuron development; peripheral nervous system axon regeneration; positive regulation of axon extension; positive regulation of microtubule polymerization; positive regulation of neuron differentiation; regulation of postsynapse assembly; response to axon injury; response to carbohydrate; response to estradiol; response to insecticide; and 5 more
Cellular component: cytosol; plasma membrane; apical dendrite; axon; basal dendrite; cytoplasm; dendrite; hippocampal mossy fiber; microtubule; microtubule associated complex; neuronal cell body; somatodendritic compartment; synapse; cytoskeleton; dendritic spine; glutamatergic synapse; growth cone; perikaryon; perinuclear region of cytoplasm; photoreceptor outer segment; postsynapse; postsynaptic density; varicosity
Genetic constraint (gnomAD): Loss-of-function variants: 11 observed, 174.14 expected, observed/expected ratio (o/e) 0.0632, 90% interval 0.039 to 0.1. The upper end of that interval is the gene's LOEUF score, 0.1, which puts it in group 1 of 6, group 1 being the genes least tolerant of losing a copy. Missense variants: 2,508 observed, 3,106.7 expected, observed/expected ratio (o/e) 0.81, 90% interval 0.78 to 0.83. Synonymous variants: 1,038 observed, 1,175.8 expected, observed/expected ratio (o/e) 0.88, 90% interval 0.84 to 0.93.
Gene-disease validity (ClinGen):
ClinGen rates the evidence that MAP1B causes each of these diseases.
periventricular nodular heterotopia (autosomal dominant): Strong. Periventricular nodular heterotopia (PNH) is a brain malformation, due to abnormal neuronal migration, in which a subset of neurons fails to migrate into the developing cerebral cortex and remains as nodules that line the ventricular surface.
Homologues: Orthologues: chimpanzee MAP1B (99% identical), macaque MAP1B (98% identical), pig MAP1B (92% identical), dog MAP1B (92% identical), guinea pig MAP1B (91% identical), mouse Map1b (91% identical), rat Map1b (90% identical), rabbit MAP1B (85% identical), tropical clawed frog map1b (63% identical), zebrafish map1b (47% identical). Paralogues in human: MAP1A (27% identical), MAP1S (18% identical).
Diseases named in the same sentence as MAP1B in open-access papers:
MAP1B is named in the same sentence as 89 diseases in open-access papers, as found by Europe PMC text mining. Sharing a sentence is not in itself a finding about the gene and the disease. The quoted sentences say what the papers report.
Intellectual disability (10 papers, 2015 to 2025). "Mutated forms of MAP1B have been linked to intellectual disability and extensive white-matter deficits in humans." (PMID 34025352, 2021). "Pathogenic variants in the MAP1B gene have been associated with neurological impairment, including intellectual disability, attention-deficit/hyperactivity disorder (ADHD), autism spectrum disorder, brain malformations, cognitive hearing loss, short stature, and dysmorphic features." (PMID 40869917, 2025). "Disease-causing variants (DCVs) in MAP1B have recently emerged as a cause of neurodevelopmental disorders characterized by intellectual disability, epilepsy, and cortical malformations, including periventricular nodular heterotopia (PVNH) and polymicrogyria (PMG)." (PMID 40874586, 2025). "In addition, genetic studies have shown that MAP1B mutations affect general cognitive ability, causing intellectual disability through a profound whole-brain deficit of white matter with likely disordered or compromised axons." (PMID 37108467, 2023). "Importantly, MAP1B has been linked to the protein KIRREL3 which is associated with autism/intellectual disability." (PMID 34025352, 2021). "Loss-of-function mutations of MAP1B were reported in patients with intellectual disability." (PMID 34093668, 2021). "Liu and colleagues proposed that MAP1B is a potential candidate for intellectual disability and ASD." (PMID 37108467, 2023). "The introduction of a functional Cr transporter in the CTD-rescue organoids leads to a reduction of GSK3β activation, a restoration of the SOX2 progenitor marker level, as well as of the highlighted proteins linked to intellectual disabilities such as PAK1 and MAP1B." (PMID 37830910, 2023). "Validated targets of miR-146a include MAP1B, which regulates AMPA receptor endocytosis, while direct targets of miR-221 include FMR1, the fragile X gene which is the most frequent cause of syndromic intellectual disability (ID) and ASD." (PMID 26753090, 2016). "In addition, we found a genomic deletion encompassing MAP1B in one patient with intellectual disability, microcephaly and seizures and deletions encompassing MYO16 in two unrelated patients with intellectual disability, autism and microcephaly." (PMID 25902260, 2015). "Noteworthily, 21 proteins are related to autism spectrum disorders (e.g. PAK2), intellectual disability (e.g. PAK1), neurodevelopmental disorders (e.g. GSK3β) and epileptic encephalopathies (e.g. MAP1B)." (PMID 37830910, 2023).
colorectal cancer (7 papers, 2015 to 2024). A primary or metastatic malignant neoplasm that affects the colon or rectum. "These provided a possible direction for future research on MAP1B: to explore the key role of missense mutations in the tumorigenesis and progression of cancer, especially colorectal cancer." (PMID 36405685, 2022). "Collectively all these results reveal that the RIMKLB gene has a positive association and correlation with AKT3, MPDZ, PKD2, and MAP1B to upregulate the gene expression to induce the development of colorectal cancer." (PMID 35444692, 2022). "Early studies showed that knockdown of Bcl11a in cultured neurons increased axon branching, multi-axon formation, and dendrite outgrowth, which could be rescued by the overexpression of deleted in colorectal carcinoma (Dcc) and microtubule-associated protein 1b (Map1b)." (PMID 38392344, 2024). "We found that draxin-induced growth cone collapse critically depends on draxin receptors (deleted in colorectal cancer, DCC), inhibition of protein kinase B/Akt, activation of GSK-3β (glycogen synthase kinase-3β) and the presence of microtubule-associated protein MAP1B." (PMID 25775433, 2015). "Knockdown of BCL11A-L, downregulates expression of MAP1B and the axon-guidance receptor DCC (deleted in colorectal cancer), and induces axon branching, multi-axon formation, and dendrite outgrowth with suggestions that BCL11A-L plays an important role in neural circuit formation during development." (PMID 30150678, 2018).
urothelial carcinoma (7 papers, 2020 to 2025). A malignant neoplasm derived from the transitional epithelium of the urinary tract (urinary bladder, ureter, urethra, or renal pelvis). "MAP1B, one of microtubule-associated proteins (MAPs), is reported as the most significant upregulated gene in urothelial carcinoma progression." (PMID 36709279, 2023). "Study findings indicated that MAP1B overexpression was associated with adverse clinical features and could independently predict unfavorable prognostic effects, indicating its theranostic value in urothelial carcinoma." (PMID 32182788, 2020). "MAP1B (ENSG00000131711), is a microtubule-associated protein involved in several types of cancer, including non-small cell lung cancer, urothelial carcinoma, and triple-negative breast cancer." (PMID 40863726, 2025). "Overexpression of MAP1B has been found to correlate with adverse clinical outcomes and predict unfavorable prognostic factors in urothelial carcinoma and glioblastoma." (PMID 37081981, 2023). "Real-time reverse-transcription polymerase chain reaction was used to measure MAP1B transcription levels in urothelial carcinoma of the upper tract (UTUC) and the bladder (UBUC)." (PMID 32182788, 2020).
Alzheimer disease (5 papers, 2014 to 2025). A progressive, neurodegenerative disease characterized by loss of function and death of nerve cells in several areas of the brain leading to loss of cognitive function such as memory and language. "Phosphorylation at mode I sites results in a loss of microtubule-stabilizing ability and mode I phosphorylated MAP1B is also observed in neurofibrillary tangles (NFTs) and dystrophic neurites in Alzheimer's disease brains." (PMID 40222271, 2025). "Abnormal Tau interactions with mitochondrial proteins have been reported to be causal in mitochondrial dysfunction in Alzheimer's diseases, and abnormal LC3/MAP1b interaction with mitochondria resulted in mitophagy in Parkinson disease models." (PMID 25526643, 2014).
breast carcinoma (5 papers, 2006 to 2024). "Given this background, new studies focused on relating the expression of MAP1B and ERβ in Luminal A breast cancer patients will be necessary to improve the understanding of these mechanisms." (PMID 39596804, 2024). "Immunohistochemical analysis also revealed that the expression of MAP1B protein was higher in TNBC patient tissues than in milder luminal breast cancer patients." (PMID 38353696, 2024). "Two proteins linked to the dynamics of the microtubule cytoskeleton, MAP1B and TUBA1A, were found to have unfavorable effects on patients with breast cancer when their expression levels were high in this study." (PMID 39596804, 2024). "This suggested that MAP1B expression and ERα were inversely correlated in patients with breast cancer." (PMID 39596804, 2024). "Next, we surveyed the correlation between MAP1B expression levels and relapse-free survival of breast cancer patients using a publicly available database." (PMID 38353696, 2024). "A similar mechanism might underlie the tumor growth retardation caused by MAP1B depletion; MAP1B might be required for the trafficking of NMDAR and/or other growth-dependent receptors in breast cancer cells to promote invasive tumor growth in vivo." (PMID 38353696, 2024). "In this study, we used a breast cancer model to examine the effects of radiation alone or in combination with estrogens on the expression of genes linked to cell motility, such as ADAM12, CYR61, FLRT2, SLIT2, VNN1, MYLK, MAP1B, and TUBA1A." (PMID 39596804, 2024). "Bioinformatic analysis indicated that FLERT2, SLIT2, VNN1, MAP1B, MYLK, and TUBA1A gene expressions were found to be higher in normal tissue than in tumor tissue of breast cancer patients." (PMID 39596804, 2024). "Moreover, autophagic degradation of Tks5 due to a lack of MAP1B may, at least in part, cause tumor cell growth retardation because Tks5 has been reported to be necessary for breast cancer cell growth." (PMID 38353696, 2024). "According to a bioinformatic study, the expression of the genes FLRT2, SLIT2, VNN1, MAP1B, MYLK, and TUBA1A was found to be higher in normal tissue than in malignant tissue in patients with breast cancer." (PMID 39596804, 2024). "We found that MAP1B is highly expressed in the most aggressive and deadliest breast cancer subtype, triple-negative breast cancer (TNBC), but not in other subtypes." (PMID 38353696, 2024). "However, the MAP1B and ESR2 gene expression levels were positively correlated in Luminal A breast cancer patients." (PMID 39596804, 2024). "Lastly, the survival of breast cancer patients was significantly influenced by the high expression of TUBA1A in Luminal B patients and MAP1B in Luminal A patients, which corroborated the importance of these markers and the expression of genes and proteins related to cell motility." (PMID 39596804, 2024). "However, the 7 genes matching this description (Clasrp, Cyp3a44, Gpr18, Lrp2, Map1b, Spen, and Ttn), are neither known breast cancer or pan‐cancer driver genes nor directly involved with the activation of MAPK/ERK signaling." (PMID 35398967, 2022).
glioblastoma (5 papers, 2020 to 2023). The most malignant astrocytic tumor (WHO grade IV). "And phosphorylation of MAP1B associate with drug sensitive in human glioblastoma." (PMID 36709279, 2023). "mTORC2-associated interactome showed actin-binding proteins and microtubule-associated proteins significantly changed depending on mTORC2 activity level in glioblastoma, including Myosin-9/MYH9, Plectin/PLEC and MAP1B." (PMID 36552831, 2022).
Parkinson’s (5 papers, 2014 to 2024). "Irregular Cdk5 activation and its phosphorylation of substrates as tau, MAP2, and MAP1b have been associated with pathological conditions, such as Alzheimer and Parkinson’s diseases." (PMID 35182267, 2023). "MAP1B plays a crucial role in neuronal development, and mutations in MAP1B are correlated with the development of a variety of neurological diseases including Parkinson’s, schizophrenia, and periventricular nodular heterotopia." (PMID 39305956, 2024). "It is also reported that persistent tau reduction resulted in iron accumulation in dopaminergic neurons within the SN with age‐dependent loss of SN neurons and parkinsonism phenotypes, whereas the increased levels of MAP1B were discovered that may be a compensatory mechanism." (PMID 38020716, 2023). "We found that MAP1B interacts with LRRK2 and protects against Parkinsonism, both of which may be therapeutically targeted for the treatment of PD." (PMID 38020716, 2023).
epilepsy (4 papers, 2018 to 2025). A brain disorder characterized by episodes of abnormally increased neuronal discharge resulting in transient episodes of sensory or motor neurological dysfunction, or psychic dysfunction. "We analyzed three epilepsy-associated variants of MAP1B and found that the longest variant (HC1-1103) displayed robust microtubule binding, likely due to the presence of the MTBD, while the shorter variants lacking the MTBD, HC1-532, and HC1-303, did not bind microtubules." (PMID 39305956, 2024). "In addition, we identified a number of genes altered in PTE+ astrocytes that are known to be involved in differentiation, migration, and cell morphology, of which several are associated with epilepsy (i.e., Eml1, Map2, Map1b, Sema3f, and Ptn)." (PMID 37174647, 2023). "Furthermore, the three epilepsy-associated variants have different microtubule-binding affinities, suggesting that the manifestation of the disease may be related to an overall decrease in functional MAP1B protein." (PMID 39305956, 2024). "However, only one MAP1B LoF carrier, in our cohort, has diagnosed epilepsy (FAM1-D3)." (PMID 30150678, 2018).
giant axonal neuropathy (4 papers, 2011 to 2024). A rare inherited disorder affecting the neurofilaments. "MAP1B has been associated with human neurological disorders, such as giant axonal neuropathy, fragile-X syndrome, and spinocerebellar ataxia type 1." (PMID 25902260, 2015). "MAP1b has also been reported to participate in the pathogenesis of Fragile X syndrome and Giant axonal neuropathy." (PMID 21645326, 2011). "Abnormal accumulation of MAP1B-LC leads to neuronal death in Giant Axonal Neuropathy (GAN) knockout (KO) mice." (PMID 21645326, 2011). "However, in a giant axonal neuropathy model, overexpression of MAP1B in cortical neurons led to development of cell death characteristics, suggesting its link with neurodegeneration and promotion of cell death in diseases such as Alzheimer’s." (PMID 38474262, 2024).
lung carcinoma (4 papers, 2017 to 2024). "For example, the epigenetic repression of MAP1B was associated with the development of lung cancer in patients with chronic obstructive pulmonary disease." (PMID 32444802, 2020). "An epigenome-wide association study has showed an increased methylation and the subsequent down-regulation of coiled-coil-domain-containing 37 (CCDC) and microtubule-associated protein 1B (MAP1B) genes, leading to augmented cell proliferation and lung cancer risk." (PMID 38337438, 2024).
autism (3 papers, 2015 to 2026). Persistent deficits in social interaction and communication and interaction as well as a markedly restricted repertoire of activity and interest as well as repetitive patterns of behavior. "We searched for naturally occurring MAP1B gene duplication or triplication cases in human disease databases, including ClinVar46 and DECIPHER24, as well as Simons Foundation Autism Research Initiative (SFARI)." (PMID 37365192, 2023).
autism spectrum disorder (3 papers, 2023 to 2025). A spectrum of developmental disorders that includes autism, and Asperger syndrome. "For instance, MAP1B, a microtubule filament protein, the prominent target of FXR1, is also targeted by FMRP and is associated with autistic spectrum disorder and autophagy." (PMID 38709899, 2024).
Cognitive impairment (3 papers, 2018 to 2020). Abnormal cognition is characterized by deficits in thinking, reasoning, or remembering. "Two additional stop-gain variants in MAP1B were found, in two independent families, which confirmed the association with cognitive impairments." (PMID 30150678, 2018). "Only one variant, a frameshift variant causing premature truncation (E712KfsTer10) of MAP1B was found to associate with the cognitive impairments in this family (genome-wide corrected P = 0.022)." (PMID 30150678, 2018). "However, it is clear that under- or over-connectivity can result in cognitive deficits and that MAP1B is a critical intermediary, demonstrated by the loss of BCL11A-L and FMRP." (PMID 30150678, 2018). "This establishes that LoF variants in MAP1B associate strongly with cognitive impairments." (PMID 30150678, 2018). "Impairment of MAP1B cleavage by abnormal CAPN10 might well cause cognitive disorders, as MAP1B has been shown to coordinate microtubule and actin filament remodeling in neural cells." (PMID 30425305, 2018). "SMOC1, YWHAZ, ALDOA and MAP1B emerged as biomarker candidates that could best discriminate between individuals with AD and non-AD cognitive impairment as well as Tau/β-amyloid ratio." (PMID 32514259, 2020). "Namely, SMOC1, ALDOA, MAP1B and YWHAZ proteins emerged as biomarker candidates with low coefficients of variation that could best discriminate AD from non-AD cases with cognitive impairment as well as predict individuals with high Tau/Aβ ratio in CSF." (PMID 32514259, 2020).